PTPDC1 (protein tyrosine phosphatase domain containing 1)
Description:
May play roles in cilia formation and/or maintenance.
Synonyms: PTP9Q22; FLJ37312
Tractability: PROTAC: ubiquitination databases record sites on it; its protein half-life has been measured.
Gene: Protein-coding gene on chromosome 9 (94,030,794 to 94,109,856, forward strand). Ensembl gene ENSG00000158079.
Subcellular location (Human Protein Atlas): Nucleoplasm; Cytosol
Gene Ontology:
Molecular function: protein binding; protein tyrosine phosphatase activity
Biological process: cilium assembly
Cellular component: cytoplasm
Genetic constraint (gnomAD): Loss-of-function variants: 41 observed, 63.51 expected, observed/expected ratio (o/e) 0.65, 90% interval 0.5 to 0.84. The upper end of that interval is the gene's LOEUF score, 0.84, which puts it in group 3 of 6, group 1 being the genes least tolerant of losing a copy. Missense variants: 872 observed, 978.53 expected, observed/expected ratio (o/e) 0.89, 90% interval 0.84 to 0.94. Synonymous variants: 326 observed, 363.72 expected, observed/expected ratio (o/e) 0.9, 90% interval 0.82 to 0.98.
Homologues: Orthologues: chimpanzee PTPDC1 (99% identical), macaque PTPDC1 (95% identical), pig PTPDC1 (79% identical), rabbit PTPDC1 (79% identical), dog PTPDC1 (77% identical), mouse Ptpdc1 (74% identical), guinea pig PTPDC1 (74% identical), rat Ptpdc1 (73% identical), zebrafish zgc:77752 (27% identical), Caenorhabditis elegans ptp-8 (17% identical). Paralogues in human: CDC14A (13% identical), PALD1 (13% identical), CDC14B (11% identical), CDC14C (10% identical), PTP4A1 (6% identical), PTP4A2 (6% identical), PTP4A3 (5% identical), CDKN3 (5% identical).
Diseases named in the same sentence as PTPDC1 in open-access papers:
PTPDC1 is named in the same sentence as 6 diseases in open-access papers, as found by Europe PMC text mining. Sharing a sentence is not in itself a finding about the gene and the disease. The quoted sentences say what the papers report.
dementia (1 paper, 2023). Loss of intellectual abilities interfering with an individual's social and occupational functions. "While the precise function of the Protein tyrosine phosphatase domain-containing 1 (PTPDC1) protein is yet to be elucidated, its down regulation has been associated with phenotypes such as obesity and dementia." (PMID 37229194, 2023).
gastric cancer (1 paper, 2021). A primary or metastatic malignant neoplasm involving the stomach. "We further used the ROC curve to evaluate the diagnostic value of circ-PTPDC1 in distinguishing gastric cancer from adjacent noncancerous tissues." (PMID 34803498, 2021).
cancer (3 papers, 2016 to 2024). A tumor composed of atypical neoplastic, often pleomorphic cells that invade other tissues. "In line with the expression level of circ-PTPDC1 in cancer and pericarcinomatous tissues, we divided it into high-expression and low- expression group." (PMID 34803498, 2021). "Until now, there has not been any study of the role of PTPDC1 in cancer." (PMID 38612874, 2024). "In particular, the overexpression of lnc-PTPDC1-7, lnc-USP25-2, and lnc-MON2-2 that overlap host genes for members of the let-7 family may somehow be related to this miRNA downregulation often detected in cancer." (PMID 26895470, 2016).
tumor (1 paper, 2021). "We confirmed the expression of PTPDC1 in normal and tumor tissue with UALCAN and TCGA portal firstly." (PMID 34803498, 2021). "Our study identifies a new circular RNA, termed circ-PTPDC1 that is up-regulated in tumor tissues, cells and plasma of GC patients, and can act as a sponge of miR-139-3p to regulate the expression of ELK1." (PMID 34803498, 2021). "Importantly, we identified that circ-PTPDC1 promotes tumor upgrowth and metabasis in vivo." (PMID 34803498, 2021).
PTPDC1 also shares sentences with these, for which no sentence is quoted: breast carcinoma (1 paper); Obesity (1).